IGHV3-49 (immunoglobulin heavy variable 3-49)
Description:
V region of the variable domain of immunoglobulin heavy chains that participates in the antigen recognition. Immunoglobulins, also known as antibodies, are membrane-bound or secreted glycoproteins produced by B lymphocytes. In the recognition phase of humoral immunity, the membrane-bound immunoglobulins serve as receptors which, upon binding of a specific antigen, trigger the clonal expansion and differentiation of B lymphocytes into immunoglobulins-secreting plasma cells. Secreted immunoglobulins mediate the effector phase of humoral immunity, which results in the elimination of bound antigens. The antigen binding site is formed by the variable domain of one heavy chain, together with that of its associated light chain. Thus, each immunoglobulin has two antigen binding sites with remarkable affinity for a particular antigen. The variable domains are assembled by a process called V-(D)-J rearrangement and can then be subjected to somatic hypermutations which, after exposure to antigen and selection, allow affinity maturation for a particular antigen.
Synonyms: IGHV349; VH
Gene: Immunoglobulin variable (V) gene on chromosome 14 (106,556,936 to 106,557,477, reverse strand). Ensembl gene ENSG00000211965.
Subcellular location: Secreted; Cell membrane
Gene Ontology:
Molecular function: antigen binding
Biological process: immunoglobulin mediated immune response
Cellular component: extracellular region; plasma membrane
Homologues: Orthologues: macaque IGHV3-49 (78% identical), mouse Ighv7-3 (74% identical), mouse Ighv7-1 (70% identical), mouse Ighv7-4 (69% identical), mouse Ighv7-2 (66% identical). Paralogues in human: IGHV3-73 (87% identical), IGHV3-72 (85% identical), IGHV3-15 (84% identical), IGHV3OR15-7 (82% identical), IGHV3-23 (81% identical), IGHV3-43 (79% identical), IGHV3-64 (77% identical), IGHV3-64D (77% identical), IGHV3-66 (77% identical), IGHV3-74 (77% identical), IGHV3-11 (76% identical), IGHV3-20 (76% identical), and 65 more.